MET (MET proto-oncogene, receptor tyrosine kinase)
Diseases named in the same sentence as MET in open-access papers (continued):
Sharing a sentence is not in itself a finding about the gene and the disease.
cancer (continued). "The growing involvement of MET in cancer progression and therapeutic resistance has led to the development of numerous strategies targeting MET, establishing it as a promising candidate for novel anti-cancer treatments." (PMID 39769452, 2024). "The complex interplay among the epidermal growth factor receptor (EGFR) and hepatocyte growth factor receptor (HGFR/MET) resulted in dysregulation and was associated with cancer pathogenesis and therapeutic resistance." (PMID 39619995, 2024). "In vitro and in vivo studies have demonstrated that the HGF/MET pathway plays a crucial role in cancer growth, invasion, metastasis, and drug resistance across various cancers." (PMID 38596618, 2024). "Capmatinib and savolitinib, selective MET inhibitors, are widely used to treat various MET-positive cancers." (PMID 38892160, 2024). "In other papers, reduced MET protein levels inhibit cancer cell growth and induce apoptosis in various cancer cells." (PMID 39519229, 2024). "It has been found that concurrent c-MET inhibition enhances adoptive T cell transfer and checkpoint immunotherapies in murine cancer models by increasing the infiltration of effector T cells into tumors." (PMID 39664377, 2024). "The identification of MET as a cancer biomarker has played a significant role in the development of therapies in oncology such as MET tyrosine kinase inhibitors (TKIs), antibodies, and antibody–drug conjugates (ADCs) designed to target MET." (PMID 38675409, 2024). "As a potent c-MET inhibitor, foretinib acted on several c-MET-activated cell lines, reducing cancer growth in different animal models." (PMID 38338677, 2024). "Cancer-associated fibroblasts (CAFs) are key producers of HGF, which signals to MET-expressing cancer cells, promoting their growth." (PMID 39598385, 2024). "It has been reported that the autophagy-lysosome pathway contributes to the selective degradation of MET in cancer cells and proteasome is vital for protein degradation." (PMID 37733896, 2024). "The synergistic activation of MET and NMDARs amplifies oncogenic signaling, leading to enhanced cell motility and the ability of cancer cells to invade surrounding tissues." (PMID 39769452, 2024). "Mutations in the kinase and juxtamembrane domains of the MET Receptor Tyrosine Kinase are responsible for oncogenesis in various cancers and can drive resistance to MET-directed treatments." (PMID 39071407, 2024). "Crosstalk between the MET and EGFR pathways, involving cell survival, proliferation, and migration, has been implicated in the development and progression of cancer in certain tissues." (PMID 38654922, 2024). "It explores the potential of c-MET antagonism combined with immunotherapeutic strategies to enhance cancer treatment paradigms." (PMID 39664377, 2024). "It is essential to comprehend the fundamental mechanisms behind MET dysregulation in cancer cell plasticity while developing cutting-edge therapeutic approaches to thwart tumor development and treatment resistance." (PMID 38329598, 2024). "MET, as a proto-oncogene, can act as an independent carcinogenic factor to drive cancer development." (PMID 39605750, 2024). "A recent study found that overexpressing c-MET in cancer cells increased the secretion of CXCL1/2, G-CSF, and GM-CSF—immune factors that are crucial for neutrophil recruitment, granulogenesis, and homeostatic function." (PMID 39201787, 2024). "We also include reported cancer patients harboring primary or acquired MET fusions to understand the potential treatment options for these patients." (PMID 38195556, 2024). "It was recently reported to be involved in cancer development regulation and several studies have been made to develop c-MET-targeted agents to be employed in several malignancies." (PMID 38338677, 2024). "The induction of PD-L1 by c-MET depends on the RAS pathway and HO-1, and inhibition of c-MET signaling or PD-L1 can increase the apoptosis of cancer cells mediated by immune cells." (PMID 39664377, 2024).
cancer (continued). "Previous studies have shown that MET is a well-known direct target gene of miR-1 in various human cancers." (PMID 39221422, 2024). "TGF-β-induced EMT enhances cancer cell invasiveness and metastatic potential, with c-MET signaling synergizing to promote EMT and stem-like properties." (PMID 39664377, 2024). "The intriguing “flare effect” phenomenon, wherein MET inhibition can lead to post-treatment increases in cancer cell proliferation, underscores the dynamic nature of cancer therapeutics." (PMID 38675409, 2024). "Targeting the MET-NMDAR interaction represents a potential therapeutic strategy in cancer treatment." (PMID 39769452, 2024). "The intricate relationship between the galectin family and c-MET signaling underscores their pivotal roles in cancer biology." (PMID 39664377, 2024). "NSCLC CAFs co-cultured with EGFR mutant cancer cells activated the MET signaling pathway and/or FGF receptor, rescuing EGFR-positive cancers." (PMID 39834587, 2024). "Overall, the strategic inhibition of c-MET and pathways like mTOR show promise in treating various cancers by overcoming resistance and enhancing therapeutic outcomes." (PMID 39329778, 2024). "Aberrant MET/HGF regulation is observed in a wide variety of human cancers with a dysregulated proliferative and invasive signaling program, epithelial-to-mesenchymal transition, cell motility/migration, angiogenesis, invasion, and metastasis." (PMID 39087020, 2024). "MET is a cancer driver in solid tumours, and this receptor is involved in cancer recurrence signalling in response to human epidermal growth factor 2 (HER2) tyrosine kinase inhibitors." (PMID 38891113, 2024). "Continuing research and clinical innovation will be essential to fully realize the potential of galectin and c-MET-targeted therapies in the fight against cancer." (PMID 39664377, 2024). "These two molecules have also been explored for blocking MET activation in clinical trials or case reports including cancer patients featuring MET activation." (PMID 38892318, 2024). "When MET signaling is aberrant and deregulated, it promotes proliferation, invasiveness, and survival, sustaining both cancer onset and progression and being crucial during the formation of distant metastasis." (PMID 38892318, 2024). "MET inhibitors have been reported to be an efficient treatment regimen combined with other drugs in various cancers, including colorectal, gastric, and pancreatic." (PMID 39458991, 2024). "Future research should delineate the precise molecular pathways and interactions between galectins and c-MET in different cancer types." (PMID 39664377, 2024). "Tivantinib has been reported to inhibit cancer cell proliferation either through c-MET inhibition, microtubule inhibition, or both pathways." (PMID 39458991, 2024). "MET activation drives the malignant progression of CRC by promoting signaling cascades that mainly affect cancer cells’ survival, proliferation, migration, and invasion." (PMID 38212428, 2024). "It has been demonstrated to have antitumor activity in cancer cells overexpressing c-MET or with amplified MET, as well as in xenografts, including patient-derived xenograft (PDX) models and those resistant to other c-MET inhibitors." (PMID 39664377, 2024). "To confirm the direct impact of METi-dependent E2F1 depletion on purine synthesis, we transiently expressed E2F1 in MET-driven GTL-16 cancer cells." (PMID 38957115, 2024). "Navigating these complexities is imperative in pursuing effective c-MET-targeted immunotherapies for cancer patients." (PMID 39664377, 2024).
cancer (continued). "MET stands out as one of the most important oncogenes activated in cancer and its inhibition has been explored since the initial era of cancer-targeted therapy." (PMID 38892318, 2024). "By amplifying MET gene, cancer cells switch the downstream signaling pathway from the inhibited kinases to the overactivated MET, and then escape from TKI inhibition." (PMID 39184861, 2024). "Conversely, inhibition of c-MET was reported to activate the anti-cancer immune response by promoting the cytotoxic effects of CD8 + T cells." (PMID 38776028, 2024). "c-MET is a receptor tyrosine kinase that is involved in various cellular processes, including the cancer cell growth, survival, and metastasis." (PMID 39325320, 2024). "It was found that HGF/c-MET signaling activated the RAS/RAF pathway, down-regulated cancer cell apoptosis, and was associated with the overexpression of cytoprotective HO-1 and anti-apoptotic Bcl-2/Bcl-xL." (PMID 39664377, 2024). "The ADC demonstrated robust potency and complete efficacy in cancer cell lines with MET amplification and high c-MET expression." (PMID 39664377, 2024). "Combining MET inhibitors with EGFR inhibitors like gefitinib or erlotinib has shown enhanced efficacy in overcoming resistance in certain cancers." (PMID 39769452, 2024). "Savolitinib is an anti-cancer drug with MoA of c-MET (Hepatocyte growth factor receptor) inhibition." (PMID 39371421, 2024). "Several studies have spotlighted how c-MET overexpression and hyperactivity correlate with PD-L1 expression, facilitating cancer cells’ evasion of the immune system’s anticancer defenses." (PMID 39664377, 2024). "The drug works by overcoming resistance mechanisms to tyrosine kinase inhibitors, targeting MET as a bypass resistance pathway and engaging effector cells for an anti-cancer effect." (PMID 39598385, 2024). "A preference for HER3 among EGFR-family RTKs for MET-dependent tyrosine phosphorylation was observed in multiple MET-amplified cancer cell lines." (PMID 38675409, 2024). "Since MET is involved in cancer stemness, GC tumorspheres grown in cocultures were treated with 10 μM SU11274 for 48 h." (PMID 37887325, 2023). "HGS and its receptor tyrosine kinase MET have a role in uncontrolled cell survival, growth, and angiogenesis in cancer." (PMID 37266401, 2023). "Despite the extensive research and ongoing studies, inhibiting the cross-talk between the EGFR and MET signaling pathways in cancer remains a challenge." (PMID 37631372, 2023). "Targeting c-MET activity, either with small molecule inhibitors or RNA interference, has been shown to suppress the cancer stem-like phenotype by downregulating CSC markers, including CD133, CD44, ABCG2, Sox2, and ALDH1." (PMID 38201226, 2023). "More importantly, TBC1D10B-associated DEGs were associated with extracellular matrix (ECM) regulation and the MET gene, which were usually involved in both development and cancer progression." (PMID 36611046, 2023). "This review explores recent discoveries concerning MET alterations in cancer, elucidating their biological repercussions, discussing therapeutic avenues, and outlining future directions." (PMID 37760640, 2023). "GSEA revealed that, compared with KC mice, KSC mice had an enrichment in stem cell networks (ESC pluripotency, Wnt, Notch, Hedgehog); EMT; a pancreatic ductal cell program; cancer-associated networks; and EGFR, ERBB2/HER2, and MET signaling pathways." (PMID 37643018, 2023). "Postoperative pathology results confirmed that the expression of c-MET in the high-fluorescence signal area was high, and that local small cancer foci were present in this area." (PMID 36184713, 2023). "MET can also be overexpressed in cancers that harbor an activating genomic signature, including those with primary/secondary MET amplification, or MET exon 14 alterations." (PMID 36765572, 2023). "Among cancers driven by tyrosine kinase receptors, those relying on alterations of the MET oncogene benefit from treatment by specific inhibitors." (PMID 36697438, 2023).
cancer (continued). "The focus of our study lays on HGF as a promising prognostic marker, knowing that the HGF/MET pathway is one of the most important pro-oncogenic, pro-angiogenetic, and pro-metastatic signals in various cancer types." (PMID 37170275, 2023). "In recent times, several advances in developing innovative biomarkers of MET dysregulation in cancer have garnered enormous interest in ascertaining MET-dependent malignancies and developing effective treatment options." (PMID 37400762, 2023). "The overexpression of c-MET correlates with the maintenance of the cancer stem cell properties in HNSCC and treatment failure." (PMID 37373393, 2023). "Due to the high prevalence of c-MET hyperactivation in a variety of cancers, inhibitors have been designed to target the molecule for therapeutic purposes." (PMID 37181747, 2023). "Because of extensive preclinical research indicating a link between HGF/c-MET signaling and cancer cell survival, clinical studies targeting the c-MET axis in HNSCC have been initiated." (PMID 37373393, 2023). "c-MET is a transmembrane receptor involved in many biological processes and contributes to cell proliferation and migration during cancer invasion process." (PMID 37843660, 2023). "In the context of cancer, abnormal HGF secretion and activation, in conjunction with MET gene mutations that are closely associated with overexpression, amplification, and selective splicing, lead to the aberrant activation of the HGF/c-MET axis." (PMID 37919751, 2023). "MET is a receptor for hepatocyte growth factor, which is involved in the growth, invasion and metastasis of malignant tumours." (PMID 37445733, 2023). "Nevertheless, MET activation is not only relevant in cases of oncogene addiction: indeed, cancer cells exploit the invasive growth program to arrange and sustain an adaptive response to adverse microenvironmental conditions." (PMID 37345079, 2023). "MACC1 has been found to play key roles in cancer cell migration, invasion, epithelial-to-mesenchymal transition, and metastasis in various types of cancer, through activation of MET signaling." (PMID 37496665, 2023). "This experimental model allows to correctly evaluate the contribution of the HGF/MET axis activation to the dissemination of human cancer cells." (PMID 37345079, 2023). "Despite promising pre-clinical evidence regarding the HGF/MET pathway in numerous solid types of cancer, results in our study show a surprisingly low clinical impact of HGF expression in chRCC." (PMID 37170275, 2023). "Crizotinib, for instance, was initially developed as an MET inhibitor, but later it was found to be even more efficient in cancers with ALK rearrangements." (PMID 36839989, 2023). "For the treatment of cancers where MET is amplified/overexpressed and activated, MET inhibitors hold tremendous potential." (PMID 37400762, 2023). "Correspondingly, SYK depletion in MET-amplified cancer cells reduced the G0/G1 cell cycle arrest-induced by c-Meti, while further FRA1 knockdown reversed this reduction." (PMID 37183231, 2023). "MET gene fusions are rare oncogenic driver alterations in a variety of cancers, including hepatocellular carcinoma, gastric carcinoma, sarcoma, and NSCLC." (PMID 37296895, 2023). "The finding of strong associations between cancer drivers, such as EGFR, KRAS and MET and their associated enhancers, further stresses the importance of epigenetic and genetic interaction during tumorigenesis." (PMID 37914932, 2023). "While interpreting these findings, it is crucial to place MET amplification in the broader context of common chromosomal aberrations in cancer, such as cellular aneuploidy." (PMID 37760640, 2023).
cancer (continued). "It has been revealed that TNS4 interacts with MET signalling, a process known to enhance motility, cancer cell survival, and angiogenesis." (PMID 38134011, 2023). "Conversely, MET inhibition has been shown to enhance the effects of RT in vitro and in mouse xenograft models of cancer." (PMID 37188738, 2023). "Using CRISPR-Cas9 technology, we generated MET knock-out cancer cell lines and evaluated their invasive properties in vitro and their dissemination ability in vivo." (PMID 37345079, 2023). "MET amplification and exon 14 skipping alterations are well‐known oncogenic drivers in multiple cancer types." (PMID 37326363, 2023). "We confirm that increased and sustained MET phosphorylation in cancer cells released from kinase blockade enhances proliferation." (PMID 36697438, 2023). "Since MET became a promising anti-cancer target, several small molecule inhibitors and antibodies were tested in clinical trials against advanced HCC." (PMID 37779207, 2023). "Several clinical studies have addressed the role of the HGF/MET pathway in diverse types of cancer, such as gastric, colorectal, breast, hepatocellular, pancreatic, lung and renal cancer." (PMID 37170275, 2023). "In cancer, MET pathway activation promotes cell proliferation, survival, angiogenesis, migration, and invasion." (PMID 36999986, 2023). "We previously reported differential responses to MET-targeting TKIs and neutralizing antibodies using cancer cell lines bearing different levels of MET expression." (PMID 37779207, 2023). "MET alterations, in addition to their primary cancer driver role, can mediate resistance to other targeted therapies, such as EGFR inhibitors." (PMID 36670542, 2023). "Capmatinib, an oral adenosine triphosphate (ATP)-competitive MET inhibitor, demonstrated anti-cancer efficacy with an ORR of 68% and a median PFS of 9.69 months in treatment-naïve patients in the phase II GEOMETRY mono-1 trial." (PMID 36969059, 2023). "MET regulates the proliferation, migration, and invasion of cancer cells by mediating the pathways such as PI3K/AKT pathway, MAPK pathway, and FAK pathway." (PMID 37821801, 2023). "In view of the fact that the HGF/MET pathway is relevant in tumor progression and tumorigenesis in diverse types of cancer, it seems obvious that therapeutic approaches are expected to target either the ligand (HGF) or the receptor (MET)." (PMID 37170275, 2023). "As a result, current drugs that solely target the HGF/c-MET axis and the Hh pathway demonstrate only moderate efficacy in specific types of cancer." (PMID 37919751, 2023). "The HGF/MET pathway is essential in cell proliferation, motility, and the development of resistance to cancer therapy." (PMID 36751113, 2023). "Recently, MET has been suggested as one of the top five proteins to focus on in targeted cancer therapies." (PMID 37760640, 2023). "MET is a common target in three of the pathways detected for miR-206 in the in silico analysis of the present study: miRNAs in cancer, proteoglycans in cancer, and transcriptional misregulation in cancer." (PMID 37569812, 2023). "Foretinib which is currently undergoing phase III studies for different cancer types, is also a multi-kinase inhibitor targeting MET, VEGFR-2, RON and FLT125." (PMID 37673888, 2023). "MET overexpression can be found in inflammation and hypoxia, leading to proliferation and migration, and is seen in a large variety of cancer types, including epithelial, mesenchymal, and hematological malignancies." (PMID 37509224, 2023). "Similar results were observed in another two tested models, one model involving MET-amplified MKN45 cancer cells with stable SYK knockdown and one model involving EGFR-mutant PC9 cells with stable SYK knockdown." (PMID 37183231, 2023). "One of the key mediators of PSC - cancer cell interactions is the hepatocyte growth factor (HGF)/c-MET pathway." (PMID 37354984, 2023).